MYO1E (myosin IE)
Diseases named in the same sentence as MYO1E in open-access papers (continued):
Sharing a sentence is not in itself a finding about the gene and the disease.
tumor (13 papers, 2016 to 2025). "The functions of MYO1E in tumor progression include enhancement of cell proliferation and loss of cell differentiation, both of which could be modulated by the MYO1E roles in cell signaling and junctional regulation." (PMID 27329840, 2016). "Normal tissues exhibited higher levels of S100A9, FTCD, POF1B, IL7R, and MYO1E, whereas tumor tissues showed increased expressions of SPINK1, CXCL9, AGFG1, and IQGAP3." (PMID 41578779, 2025). "These graphs confirm our observations that CK14 staining intensity is relatively high around the periphery of Myo1e KO tumor acini but is low or less pronounced in the Myo1e WT tumor acini." (PMID 27329840, 2016). "MYO1E-null tumors exhibited decreased expression of the markers of cell proliferation, which was recapitulated in primary tumor cells derived from MYO1E-null mice." (PMID 27329840, 2016). "Consistent with our observations in tumors, the fraction of Ki-67 positive cells was lower in the MYO1E KO tumor cell cultures (p<0.001)." (PMID 27329840, 2016). "Conversely, ZONAB was enriched at the cell-cell junctions of the MYO1E KO tumor cells, while its localization in the MYO1E WT tumor cells was mainly cytoplasmic, with some nuclear localization." (PMID 27329840, 2016). "The differences in cell proliferation rates were further confirmed using in vitro analysis of Ki-67 staining in cultured tumor cells isolated from MYO1E WT and KO PyMT mice." (PMID 27329840, 2016). "By gross examination, MYO1E WT PyMT tumors appeared dense and opaque, representative of a solid, cell-filled tumor, while MYO1E KO PyMT tumors often had a cystic, translucent, fluid-filled appearance." (PMID 27329840, 2016). "To further characterize the role of MYO1E in tumor progression, we examined metastasis to the lungs, a common site of secondary tumor formation in MMTV-PyMT mice." (PMID 27329840, 2016). "Also, given the low normal expression of MYO1E in blood cells MYO1E DNA methylation has the potential to be used as circulating tumor marker in liquid biopsies." (PMID 36914720, 2023). "Targeting MYO1E activity may have therapeutic potential by preventing the metastasis of tumor cells that depend on invadosomes for migration." (PMID 32272642, 2020). "Thus, the abundance of dilated and fluid filled cysts, as opposed to a rapid increase in cell number, is likely to account for the accelerated rate of the tumor volume increase in the MYO1E KO PyMT mice." (PMID 27329840, 2016). "Since tumors formed in MYO1E KO mice contained fewer solid, cell-filled areas, and the tumor acini appeared smaller, we hypothesized that cell proliferation rate may be lower in MYO1E KO tumors." (PMID 27329840, 2016). "In addition, ZO-1-interacting transcription factor ZONAB, which regulates expression of several cell cycle regulatory proteins, including Cyclin D1, was enriched in cell-cell junctions between MYO1E KO tumor cells." (PMID 27329840, 2016). "Thus, the cell–cell junction in MYO1E WT is different compared with MYO1E KO, and may account for the distinct tumor morphology, proliferation, differentiation, and progression." (PMID 32272642, 2020). "The presence of the fluid-filled papillary regions, with well-differentiated layers of epithelial cells, suggests that MYO1E KO tumor cells may retain stable cell-cell junctions that maintain epithelial organization and allow fluid transport and accumulation in the lumens of mammary ducts." (PMID 27329840, 2016). "In addition, comparison of the regions filled with the solid sheets of cells in the tumors from 16 week old MYO1E WT and MYO1E KO PyMT mice shows that many of MYO1E KO PyMT tumor acini remained positive for the basal cell marker, CK14, compared to the minimal CK14 staining in the WT tumors." (PMID 27329840, 2016).
tumor (continued). "As the tumor progressed, pro-inflammatory neutrophils (i.e. Ccl3- and Mmp8+ neutrophils) infiltrated the TIME of the SC models, whereas angiogenic neutrophils (i.e. Myo1e+ neutrophils) remained the predominant type of immune cell in the TIME of the BOT models." (PMID 40899264, 2025). "In the solid areas of MYO1E WT tumors, Cyclin D1-positive cells were distributed throughout the tissue, while in the tumors lacking MYO1E, Cyclin D1-positive cells were confined to the ducts and the periphery of tumor acini." (PMID 27329840, 2016). "This is indicative of the increased rate of tumor enlargement in mice lacking MYO1E, which displayed an average rate of volume change of 505 mm3/week by 9 weeks after tumor detection, compared to an average of 136 mm3/week for MYO1E WT PyMT tumors." (PMID 27329840, 2016). "Both MYO1E WT and KO tumor cells showed nuclear localization of YAP1, with no obvious differences in localization, suggesting that the extent of activation of YAP-mediated signaling pathways is likely to be similar." (PMID 27329840, 2016). "A significant co-occurrence of an upregulation of the mRNAs of MYO10, MYH9, MYO1E and TGFB1 was observed in the LUSC patients of the TCGA cohort, suggesting that the exposure of tumor cells to elevated levels of TGFβ might have stimulated upregulation of motility and invasion-related myosins." (PMID 29934580, 2018). "Overall, our data shows that tumor latency is increased in the absence of MYO1E expression, but intriguingly, the lack of MYO1E may enhance the rate at which tumors increase in volume." (PMID 27329840, 2016).
cancer (10 papers, 2016 to 2024). A tumor composed of atypical neoplastic, often pleomorphic cells that invade other tissues. "While there is limited data on MYO1E methylation, few studies showed that hypomethylated MYO1E is associated with more aggressive forms of cancer." (PMID 36914720, 2023). "In only a single variant in the gene MYO1E was the prevalence in healthy individuals significantly lower than in individuals with cancer (p value = 0.04)." (PMID 32778766, 2020). "Indeed, in the LUSC patients of the TCGA cohort the second and third most regulated genes encoding myosins were MYH9 and MYO1E, which were previously implicated in cancer progression." (PMID 29934580, 2018). "After forward search and backward search, we identified a set of five differentially expressed genes (LAMC2, TSPAN1, MYO1E, MYOF, SULF1) in Cancer/Normal that was optimized for diagnostic ability." (PMID 39850570, 2024). "Using the TCGA RNA seq data and DNA methylation data for the cg13887966 probe from LUAD and LUSC, we assessed the MYO1E RNA expression and the MYO1E DNA methylation by cancer stage." (PMID 36914720, 2023). "Despite its importance, only Myo1e has monoclonal antibodies available in the market for cancer treatment, as revealed by a thorough search among the main manufacturers." (PMID 35409272, 2022). "Nonetheless, exosomal proteins previously reported to be associated with vesicle secretion in cancer cell line supernatants (RAP1A, RAP1B, VAMP1, MYH7, MYO18a, MYOLPF, MYO1E, VPS13B, HSP70) were identified in our samples." (PMID 30764491, 2019). "Our proposed pan-cancer signature contains the probeset 203072_at (MYO1E gene ENSG00000157483, myosin IE) that is present twice in our signature because it is located both in the sigVanLaar2010 signature for colorectal cancer and in the sigHallett2012 signature for breast cancer." (PMID 36329531, 2022). "MYO1E and MYOF, involved in actin-based intracellular trafficking and vesicle transport, respectively, play key roles in cancer cell membrane dynamics and migration." (PMID 39850570, 2024). "MYO1E directly interacts with FAK, a protein involved in many biological processes, including cancer." (PMID 32272642, 2020). "Taken together, these observations strongly support that MYO10, MYH9 and MYO1E play essential and non-redundant roles in the functionality of the invasion machinery in cancer." (PMID 29934580, 2018). "CUVs from the genes MYO1E, SARDH and ISLR appeared in two distinct individuals with cancer from this non-Caucasian cohort, while CUVs from PCDHB16 and known CPG BMPR1A appeared in a single individual with cancer." (PMID 32778766, 2020).
kidney disease (9 papers, 2013 to 2026). "Missense mutations in the human MYO1E gene, encoding molecular motor protein myosin 1e (Myo1e), are associated with kidney disease." (PMID 26092123, 2015). "Our results suggest that Myo1e dysfunction might lead to shape alteration and functional impairment in podocytes, impairment of the glomerular filtration barrier, and finally proteinuria and kidney disease via actin cytoskeleton rearrangement." (PMID 23977349, 2013).
infection (2 papers, 2020 to 2022). The state of being infected such as from the introduction of a foreign agent such as serum, vaccine, antigenic substance or organism. "In response to infection, in male mice, the TACC2, BUB1B, ATP5MC3, and MYO1E, and in female mice, the CAP1, MRPL2, COX5A, KLHL21, PDIA6, TSPO, and USP14 had direct interaction with TP-53." (PMID 35844510, 2022).
genetic disorders (1 paper, 2025). "The authors concluded that the phenotype was a consequence of the two distinct genetic disorders, rather than one mutation enhancing the other, pleading for a digenic inheritance of COL4A5 and MYO1E variants in this case." (PMID 40003707, 2025).
inflammation (1 paper, 2013). Aberrant reaction of the microcirculation characterized by movement of fluid and leukocytes from the blood into extravascular tissues. "The authors found that MYO1E knock-down mice exhibited proteinuria, signs of chronic renal injury, and kidney inflammation." (PMID 23977349, 2013).
MYO1E also shares sentences with these, for which no sentence is quoted: adenocarcinoma (1 paper); amyloid (1); anencephaly (1); atherosclerosis (1); cholangitis (1); ciliopathies (1); Cirrhosis (1); colon cancer (1); colorectal cancer (1); coronary artery disease (1); cystic kidney disease (1); dyslipidemia (1); gastrointestinal tumors (1); glomerulosclerosis (1); head and neck cancer (1); head and neck squamous cell carcinoma (1); Hypertension (1); neural tube defect (1); neurodegenerative disease (1); pancreatic adenocarcinoma (1).